CD200 (CD200 molecule)
Diseases named in the same sentence as CD200 in open-access papers (continued):
Sharing a sentence is not in itself a finding about the gene and the disease.
infection (continued). "Flow cytometric analysis 21 days post infection showed that expression of CD200R on activated CD4+ T cells was reduced upon treatment with α-CD200 antibodies but not in isotype-treated controls indicating the specificity of the CD200 blocking antibodies." (PMID 29915577, 2018). "To test whether downregulation of CD200 expression also occurs in splenic DCs due to LdCen−/− infection, we infected splenic DCs isolated from C57Bl/6 mice with either LdWT or LdCen−/−in vitro." (PMID 29915577, 2018). "Similarly, infection of BMDCs with LdCen−/− add back mutant induced CD200 expression to levels observed in LdWT infection, whereas LdCen−/−-infected BMDCs showed reduced expression of CD200 compared to LdWT." (PMID 29915577, 2018). "We hypothesized that if expression of CD200 is low in LdCen−/− immunized animals relative to LdWT infection, the expression level of its receptor CD200R correspondingly would also be restrained." (PMID 29915577, 2018). "Furthermore, the level of CD200 expression in both infections was at a maximum at early infection stages, which declined at later time points." (PMID 29915577, 2018). "The CD200 expression was measured after 1, 4, 24, and 48 h post infection in DC lysates." (PMID 29915577, 2018). "We also measured the levels of pro-inflammatory cytokines IFNγ, TNFα, IL-12, and IL-1β in cultured supernatant collected after 24, 48, and 72 h post infection to verify if the levels of these cytokines have any correlation with CD200 expression in parasite-infected DCs." (PMID 29915577, 2018). "Infection of bone marrow-derived macrophages (BM-DM) and splenic macrophages up-regulated CD200." (PMID 25654642, 2015). "However our data demonstrate that MCMV benefits from this immune-regulatory pathway to persist within its mammalian host, and MCMV can actively induce CD200 expression during infection." (PMID 25654642, 2015). "Therefore, we hypothesize that improvements in outcome following infection were a result of the immunomodulatory capacity of the CD200-Fc compound." (PMID 37199641, 2023). "Additionally, to evaluate whether the resolution of the infection was affected by anti-inflammatory modulators, the expression of ho-1, nrf2 related to oxidative stress, and cd200 genes were measured by RT-qPCR." (PMID 35892656, 2022). "Furthermore, blocking of CD200 significantly reduced the Tr1 cells in LdWT infection." (PMID 29915577, 2018). "Of the two, LdCen−/− infection produced much higher proliferation than LdWT, which can be related to properties of attenuation of virulence to induce cellular proliferation that could be due to the subdued CD200 expression." (PMID 29915577, 2018). "Furthermore, in an independent experiment, we also evaluated if CD200 blocking could control proliferation of virulent parasites in an LdWT infection." (PMID 29915577, 2018). "Cell membrane markers typically expressed on monocytes/macrophages upon inflammation/infection (CD14, CD44, CD200), M1-polarization (CD80) and M2-polarization (CD163) were analyzed in the hemocyte population isolated." (PMID 38191588, 2024). "Our approach is based on the detection in isolated hemocytes from G. mellonella hemolymph of cell membrane markers typically expressed by human immune cells upon inflammation and infection, for instance CD14, CD44, CD80, CD163 and CD200." (PMID 38191588, 2024). "In DC, T cells coculture experiment, the blockade of CD200 resulted in increased proliferation of OT-II TCR transgenic CD4+ T cells in LdWT and LdCen−/− infections." (PMID 29915577, 2018). "We found that expression of CD200 and CD200R was significantly reduced in LdCen−/− infection compared to wild-type infection." (PMID 29915577, 2018). "These cells were initially characterized as CD138+IL10+ cells that exhibited increased expression of the inhibitory receptors LAG3, CD200, PD-L1, and PD-L2 as compared to CD138+IL10- cells and were the predominant source of IL-10 produced in response to infection." (PMID 38155972, 2023).
infection (continued). "In particular, the interaction between CD200 expressed on AM and CD200R expressed on the alveolar epithelium is necessary for myeloid restraint and aid in AM-mediated inflammation resolution post-infection." (PMID 36433992, 2022). "Additionally, immunization with centrin-deleted L. donovani resulted in CD200/CD200R downregulation and consequently suppression of IL-10-producing CD4+ T cells and more Th1 cells compared to WT infection." (PMID 33776999, 2021). "Upon in vitro infection of bone marrow macrophages, Leishmania-induced increased levels of CD200 in bone marrow macrophages and the lack of CD200 (BMM Cd200-/-) inhibited parasite proliferation." (PMID 33776999, 2021). "For example, Leishmania amazonensis induce the expression of CD200 both at mRNA and protein level in bone marrow macrophages, which next inhibit neighboring macrophages that express CD200R1, and thus, abrogate NO production during the infection." (PMID 33562512, 2021). "The authors demonstrated that infection of macrophages with L. amazonensis, and not with L. major, induces the expression of CD200 transcripts over time." (PMID 33776999, 2021). "Infection by Chlamydia trachomatis also increased CD200R expression in macrophages of the endometrium and CD200 expression in epithelial cells from the genital tract by regulating inflammation and suppressing collateral damage in the tissue during chronic infection, thus enabling persistence." (PMID 29607331, 2018). "Infection of BM-DM with influenza did not trigger CD200 expression, demonstrating that CD200 up-regulation is not a generic macrophage response to viruses." (PMID 25654642, 2015). "Thus, with infection an increased fraction of the total activated T cells (CD44hi) upregulated and co-expressed CD200R and CD200." (PMID 22496920, 2012). "Results showed that consistent with our in vitro blocking results, in vivo blocking with α-CD200 antibodies resulted in a significant reduction of IL-10 levels in LdWT infection (CD200R+ panel, p = 0.0065), suggesting that blocking CD200 signaling could alter the CD4+ T cell characteristics." (PMID 29915577, 2018). "Within infected SGs, CD200+ cells were predominantly large CD31+ cells (isotype controls:S1A Fig.) that were EpCAM-, suggestive of endothelial cell origin, and not EpCAM+ acinar epithelial cells in which MCMV replicates during the persistent phase of infection." (PMID 25654642, 2015). "The mAb against CD200 and CD200R but not Mincle appear to inhibit the infection of macrophage tropic SIV/SHIV in vitro." (PMID 26468886, 2015). "Importantly, we observed that SG-APCs did not support MCMV replication in vitro in accordance with the absence of detectable infection in vivo, and MCMV infection of splenic DCs did not further induce CD200 expression." (PMID 25654642, 2015).
hematologic malignancies (14 papers, 2012 to 2025). "However, CD200 expression has also been implicated in the pathogenesis of solid tumors and hematologic malignancies by mediating immunosuppression of the innate and adaptive immune responses." (PMID 38137547, 2023). "Despite that the over-expression of CD200 has been implicated in the pathogenesis of solid tumors, hematological malignancies and its expression is indicative of poor prognosis; very few studies have investigated its accuracy in MDS patients; which substantially differ from them." (PMID 32856848, 2020). "The fact that CD200 overexpression is a predictor of poor prognosis in a number of hematologic malignancies supports our data." (PMID 30800162, 2019). "Its ligand, CD200 (OX2), is a glycoprotein expressed on a broad number of cell types, including solid tumors and hematologic malignancies." (PMID 27242794, 2016). "Ibrutinib can also down-regulate CD200 (OX2) expressions in hematological malignancies." (PMID 36209106, 2022). "Notably, CD200 was originally identified as a tolerogenic immune-checkpoint factor involved mainly in hematological malignancies." (PMID 31627350, 2019).
neurodegenerative disease (9 papers, 2013 to 2024). A disorder of the central nervous system characterized by gradual and progressive loss of neural tissue and neurologic function. "Research results have shown that the reduction of anti-inflammatory CD200/CD200R is a potential mechanism leading to chronic inflammation in neurodegenerative diseases, including ALS." (PMID 39337251, 2024). "Studies in animal models have shown a decrease in CD200 expression in neurodegenerative diseases, supporting it as a therapeutic target." (PMID 39337251, 2024). "In neurodegenerative diseases, such as AD, CD200 is downregulated in human brains, and forced overexpression in the brain of CD200 promotes neurogenesis and ameliorates pathology in a mouse model of AD." (PMID 33924200, 2021). "In this view, neurodegenerative diseases are depend on the same innate immune pathway, chronically activating microglia through CD200 downregulation." (PMID 31790427, 2019). "In contrast to neurodegenerative diseases, sciatic nerve injury probably activated endogenous regulatory mechanisms including upregulation of CD200/CD200R." (PMID 26891688, 2016). "Synaptic plasticity is impaired by exaggerated inflammatory responses and microglia activation during central nervous system (CNS) injury and neurodegenerative diseases, and the CD200/CD200R signaling pathway plays an important role in regulating microglia activation and inflammatory factor release." (PMID 32473633, 2020). "CD200 signaling has been discussed for decades as an important mechanism in neuroinflammatory conditions, but the jury is still out on whether CD200 could be important target to use in ischemic brain injury and neurodegenerative diseases." (PMID 30319362, 2018). "Additionally, aging leads to a depressed CD200 expression and microglial activation, favoring a pro-neurodegenerative disease environment." (PMID 24032006, 2013).
neurological disorders (5 papers, 2014 to 2022). "Since we found increased CD200 levels and the signaling of CD200/CD200r has been associated with the modulation of microglia activation and synaptic plasticity in other neurological diseases, we evaluated how exposure to ACM Meth was affecting synaptic proteins." (PMID 35159165, 2022). "In addition, to our knowledge, little attention has been paid to the expression of the different CD200 and CD200R1 mRNA variants or protein isoforms in neurological disorders." (PMID 35296683, 2022). "To shed light on this issue, we studied the mRNA expression of CD200 and CX3CR1 (also known as fractalkine receptors), which have been associated with inhibitory actions on brain microglia, and MCP-1, a potent chemokine which has been implicated in different neurological disorders." (PMID 24565378, 2014). "Among peptides active in neurological diseases, a fragment of NCAM protein, named FGL peptide, induced the secretion of IL-4 from microglial cells leading to the increase of CD200 and to the inversion of the age related decline of hippocampus in vivo." (PMID 30208640, 2018).
bacterial infection (3 papers, 2015 to 2023). "To explore the role of CD200 in macrophage responses to S. aureus, we first detected the expression pattern of CD200 during bacterial infection." (PMID 30717437, 2019). "Given the importance of macrophages in innate immunity against bacterial infection, we then analyzed the effect of CD200 on macrophage bactericidal activity." (PMID 30717437, 2019). "Since the inflammatory response is primarily triggered upon bacterial infection, we next explored the potential role of CD200 in regulating the production of inflammatory cytokines by S. aureus-infected macrophages." (PMID 30717437, 2019). "Apoptotic cells expressing CD200 can reduce the innate immune response to secondary bacterial infection." (PMID 26265006, 2015). "This benefit is not due to increasing the area under the concentration-time curve (AUC) of the antibiotic, suggesting the immunomodulatory nature of CD200-Fc treatment is playing an important role by potentially controlling the overactive immune response seen with many lethal bacterial infections." (PMID 37199641, 2023). "The inhibitory effects of CD200 on the production of proinflammatory cytokines suggested that it might promote an M1- to M2-phenotype transition during bacterial infection." (PMID 30717437, 2019).
immunodeficiencies (3 papers, 2021 to 2025). "Similar results imply that the dysregulation of the CD200/CD200R axis may be involved in the pathogenesis of several immune diseases." (PMID 33804413, 2021). "Additionally, miR-326 and CD4+CD200+ cells, as well as miR-486 and sCD200R, exhibited significant differences in correlation coefficient values, suggesting possible changes in pathways regulating the immune response that depend on the CD200/CD200R axis in different types of immunodeficiencies." (PMID 41148792, 2025). "Moreover, dysregulation of the CD200/CD200R axis may be involved in the pathogeneses of several immune diseases." (PMID 33804413, 2021).
blood cancers (2 papers, 2016 to 2023). "CD200 has both diagnostic and prognostic significance in hematological neoplasms." (PMID 26910908, 2016).
cardiovascular disease (2 papers, 2013 to 2021). "CD200 recently emerged in the Framingham Heart Study and 2 other cohorts as being potentially relevant in cardiovascular disease." (PMID 33975450, 2021).
brain diseases (1 paper, 2020). "The CD200/CD200R signaling pathway plays an important role in neurological recovery by modulating synaptic plasticity during multiple brain disorders." (PMID 32473633, 2020). "The interaction between CD200 and CD200R1 is critical for inhibiting microglial activation and localized neuroinflammation during the pathological development of several brain diseases, including Parkinson’s disease, optic nerve crush, and germinal matrix hemorrhage." (PMID 32473633, 2020).
CNS tumor (1 paper, 2014). "To gain a better understanding of the role of CD200 in CNS tumors, we first examined CD200 mRNA expression on a variety of tissues." (PMID 25598973, 2014). "However, compared to most CNS tumors, GBMs had lower expression of CD200." (PMID 25598973, 2014).
inflammation (1 paper, 2022). Aberrant reaction of the microcirculation characterized by movement of fluid and leukocytes from the blood into extravascular tissues. "In addition, CD200/CD200R pathway shows selective regulation of acute lung inflammation and cannot completely abrogate the complex LPS-induced inflammatory response." (PMID 36591265, 2022). "Thus, CD200/CD200R pathway appears to have a selective role in controlling lung inflammation." (PMID 36591265, 2022).
pancreas (1 paper, 2019). "Considering that SPNs, ACs, and PBs represent the pancreas neoplasms that undergo differential diagnosis from PanNET, the description of the CD200 positivity in pancreatic SPNs with the same pattern described for PanNET is relevant." (PMID 30132130, 2019).
retinopathy (1 paper, 2024). "In addition, the downregulation of CD200 and IL-34, which act as immunoregulatory molecules in the serum of HS patients, could negatively influence microglia-mediated retinopathy, as has been recently demonstrated in the diabetic murine model." (PMID 38592296, 2024).
CD200 also shares sentences with these, for which no sentence is quoted: narcolepsy (4 papers); Allergy (3); Cerebral ischemia (3); colon carcinoma (3); renal cell carcinoma (3); B cell lymphoma (2); Cluster headache (2); encephalitis (2); esophageal cancer (2); follicular lymphoma (2); hematological cancers (2); Huntington disease (2); Hyponatremia (2); Infertility (2); lung large cell neuroendocrine carcinoma (2); myeloid leukemia (2); Polydipsia (2); renal carcinoma (2); splenic marginal zone lymphoma (2); Splenomegaly (2); abortion (1); acinar cell carcinoma (1); adenocarcinoma (1); adenomyosis (1); allergic asthma (1); alopecia areata (1); anaplastic oligoastrocytoma (1); anterior uveitis (1); Antibody Deficiencies (1); attention deficit-hyperactivity disorder (1).
A further 53 diseases each share a sentence with CD200 in 1 paper.